FOXO1 (forkhead box O1)
Diseases named in the same sentence as FOXO1 in open-access papers (continued):
Sharing a sentence is not in itself a finding about the gene and the disease.
endometrial cancer (continued). "In an endometrial cancer cell line, miR-9 was shown to significantly reduce expression of Forkhead box O1 (FOXO1), a transcription factor, while in another endometrial cancer cell line inhibition of this and several other miRNAs resulted in re-expression of FOXO1, cell cycle arrest, and apoptosis." (PMID 23335942, 2012). "A new finding recently disclosed in endometrial cancer cell lines suggested that the lack of FOXO1 expression was associated with an increased mRNA turnover with an unknown mechanism." (PMID 23946796, 2013). "In endometrial carcinoma, LINC00261 was reported to inhibit cell proliferation by promoting the expression of forkhead box protein O1 (FOXO1) through a mechanism of reducing the levels of FOXO1-targeted miRNAs." (PMID 34022894, 2021). "In endometrial cancer tissues and squamous cell carcinoma tissues, miR-186 served as an oncomir by suppressing targets P2RX7, FOXO1, APAF1, and RETREG1." (PMID 32195180, 2020). "Zou demonstrated that endometrial cancer cells show decreased levels of phospho-AMPK and total FOXO1 protein, and endometrial cancer tissues show significantly less staining of activated AMPK and higher levels of phospho-Akt compared to controls." (PMID 30211120, 2018). "In vitro, they reported that metformin treatment increased FOXO1 protein levels, decreased inhibitory FOXO1 phosphorylation, and increased FOXO1 nuclear accumulation in an AMPK-dependent manner, resulting in inhibition of endometrial cancer cell proliferation." (PMID 30211120, 2018). "Although TAMs exhibited reduced FoxO1 expression in many tumors, such as mice inoculated with MC38, Hep1-6, or LLC cells (GEO: GSE76033) and human endometrial cancer (GEO: GSE117970), the expression of FoxO1 in TAMs population remain complicated and heterozygous 46,47." (PMID 32973162, 2020). "In another report, inhibition of all miRNAs targeting FOXO1 in endometrial cancer cells with low levels of FOXO1 expression (Ishikawa cells) induced cell cycle arrest, while no significant changes were observed in endometrial cancer cells with high levels of FOXO1 (HEC-1B cells)." (PMID 36158686, 2022). "Recently, our group has followed up on these observations and could show that progesterone efficiently inhibited the expression of a Wnt/β-catenin signaling reporter plasmid (TOP/FOPflash) in the Ishikawa endometrial cancer cell line by induction of the Wnt/β-catenin inhibitors DKK1 and FOXO1." (PMID 21317462, 2010). "Our data suggest that genistein inhibits cell proliferation by inducing the expression of FOXO1, which lies in the downstream of PI3K/PKB signaling pathway, regardless of ER status in endometrial cancer." (PMID 35717540, 2022).
acne (34 papers, 2013 to 2025). An inflammatory process of the sebaceous glands which is characterized by comedones, nodules, papules and/or pustules on the skin. "Over the last 10 years, decreased FoxO1 expression has been linked to acne pathogenesis, whereas isotretinoin treatment increases FoxO1 expression in sebaceous glands of acne patients." (PMID 36585988, 2023). "Basically, a FoxO1 deficiency is a key factor in the pathogenesis of acne and promotes lipogenesis, secretion of proinflammatory cytokines, and proliferation of keratinocytes." (PMID 35889022, 2022). "A FoxO1 deficiency is widely evidenced as a key factor in the pathogenesis of acne, and a decreased expression of FoxO1 in this regard promotes lipogenesis, secretion of proinflammatory cytokines, and proliferation of keratinocytes." (PMID 35889022, 2022). "Nuclear FoxO1 deficiency has been linked to all major factors of acne pathogenesis, that is, androgen receptor transactivation, comedogenesis, increased sebaceous lipogenesis, and follicular inflammation." (PMID 27803511, 2016). "Meanwhile, activation of PI3K pathway was reported to reduce the nuclear content of the transcription factor FoxO1 deficiency, the key nutrigenomic regulator of acne target genes." (PMID 27803511, 2016). "Acne pathogenesis has recently been linked to decreased nuclear FoxO1 levels and increased mTORC1 activity." (PMID 23800068, 2013). "Nuclear deficiency and cytoplasmic expression of FoxO1 are increased in the sebaceous glands of patients with acne compared to the healthy control group, which is associated with increased serum IGF-I levels and activation of the mammalian target of rapamycin complex 1 (mTORC1)." (PMID 34418600, 2021). "Although the mechanism underlying the FoxO3a-mediated anti-acne effect is unclear, FoxO1 may exert its effect partly by the inhibition of the mTORC1 signaling pathway." (PMID 34418600, 2021). "Interestingly, isotretinoin, one of the major acne treatments, is able to deeply influence mTORC1 pathway with its major effects linked to modifications of PI3K/AKT/FoxO1 signalling, further confirming their important role in acne development." (PMID 25977937, 2015). "Acne is a chronic skin disease, affecting the pilosebaceous units, with multifactorial pathogenesis including hormonal influence, the immunological state of the host, diet, deregulation of insulin-like growth factor, excessive sebum production and FoxO1 deficiency." (PMID 34680552, 2021). "IGF-1 is another crucial hormonal driver, influencing acne by downregulating the nuclear transcription factor forkhead box protein O1 (FoxO1), which, in turn, increases lipogenesis and androgen receptor transduction." (PMID 38791344, 2024). "Analysis of skin biopsies from these participants revealed a decrease in IGF-1 levels alongside an increase in FoxO1 gene expression, suggesting a positive regulatory effect on acne-related markers." (PMID 38791344, 2024).
acne (continued). "Oral administration of Lactobacillus can reduce insulin-like growth factor 1 (IGF-1) and increase forkhead box protein O1 (FoxO1) expression in the skin, improving the condition of acne." (PMID 37828993, 2023). "Among many regulatory effectors, AKT phosphorylates and thereby inactivates the transcription factors FoxO1 and FoxO3, which are predicted to play a key role in the pathogenesis of acne." (PMID 37998335, 2023). "After 12 weeks of treatment, changes in expression of IGF-1 and FoxO1 genes were compared in skin areas with acne lesions." (PMID 35889022, 2022). "By upregulating the FoxO1 transcription factor, the mTORC signal was engaged in the therapeutic response to isotretinoin or metformin treatment for acne." (PMID 35163615, 2022). "The PI3K/Akt/FoxO1/mTORC1 of the Mammalian Target of Rapamycin (mTOR) C1 pathway induced by IGF-1 is known to be involved in the pathogenesis of acne." (PMID 35966699, 2022). "The cytoplasmic FoxO1 expression was much higher in acne patients than in controls, which exhibited nuclear expression in lesional skin biopsies." (PMID 35163615, 2022). "Increased growth factors during puberty and sustained growth factor signals due to WD stimulate the PI3K/Akt cascade in the sebaceous glands of patients with acne, increasing the nuclear phosphorylation of FoxO1 and their export into the cytoplasm." (PMID 34418600, 2021). "A study has demonstrated the potential association of IGF-I, mammalian target of rapamycin (mTOR), and FoxO1 in the pathogenesis of acne via immunohistochemical detection." (PMID 34418600, 2021). "Nuclear FoxO1 and FoxO3a in the sebaceous glands of patients with acne are upregulated by isotretinoin, a drug for acne treatment." (PMID 34418600, 2021). "Currently used anti-acne drugs also show therapeutic efficacy via the nuclear localization of FoxO1 and inhibition of mTORC1." (PMID 34418600, 2021). "According to a recent clinical study, consumption of L. rhamnosus SP1 for 12-weeks led to decreased IGF-1 and increased FOXO1 gene expression that ultimately resulted in alleviation of acne manifestations in adult patients." (PMID 30959761, 2019). "Insulin, insulin-like growth factor-1 (IGF-1), and defective nuclear transcription factor forkhead box protein O1 (FOXO1) promote acne by stimulating sebaceous lipogenesis and androgen signaling." (PMID 30959761, 2019). "FoxO1 has been proposed to function as a key regulator in the pathogenesis of acne as FoxO1 senses external nutrient and internal growth factor signals and relays these to FoxO1-dependent gene regulation." (PMID 23614736, 2013). "Deeper insights into the molecular interplay of FoxO1/mTORC1-mediated nutrient signalling are thus of critical importance to understand the impact of WD on the promotion of epidemic acne and more serious mTORC1-driven diseases of civilization." (PMID 23614736, 2013). "Recently, it has been suggested that deficiency of the forkhead box transcription factor O1 (FoxO1) is linked to the pathogenesis of AV; an increase in phosphorylated FoxO1 (p-FoxO1) in the cytoplasm of cells derived from patients with acne is consistent with activation of mTORC1." (PMID 37371141, 2023).
acne (continued). "This strongly indicates that mTORC2 activation is critical for the development of acne, considering that the activated Akt by mTORC2 phosphorylates FoxO1, which promotes the nuclear-cytoplasmic translocation and the degradation of FoxO1, thus resulting in FoxO1 deficiency." (PMID 37371141, 2023). "Above all, these results illuminated that emodin inhibits the activation of the PI3K/Akt/FoxO1 pathway in human sebocytes, suggesting that emodin may stagnate acne formation by inhibiting IGF-1-induced lipogenesis." (PMID 38062074, 2023). "FoxO1 and FoxO3a may be important factors for acne treatment as their activation was observed in the sebaceous glands of acne patients during the application of an anti-acne drug." (PMID 34418600, 2021). "Taken together, these observations outline the roles of FoxO1 in the development and severity of acne, and indicate that activating FoxO1 in the sebaceous glands may be an effective approach to improve the acne symptoms." (PMID 34418600, 2021). "Therefore, AMPs may be key determinants in developing and progressing acne-associated immune responses, skin barrier integrity, and metabolic factors, like insulin/IGF-1 and PI3K/Akt/mTOR/FoxO1 signaling pathways or high glucose levels." (PMID 39744637, 2024). "Therefore, AMPs could be key determinants in regulating AV development and progression, linking acne-associated immune responses and metabolic factors, like insulin/IGF-1 and PI3K/Akt/mTOR/FoxO1 signaling pathways or glucotoxicity." (PMID 39744637, 2024). "Thus, emodin may counteract the pro-acne effects of IGF-1 by inhibiting the phosphorylation of PI3K/Akt/FoxO1 pathway, thereby downregulating the expression of lipogenic factors." (PMID 38062074, 2023). "For example, several studies found that frequent consumption of certain dairy products, carbohydrates, high GI and glycaemic load (GL) diet is a potential risk factor for acne, which could be attributed partly to the insulin-like growth factor 1 (IGF1)/FoxO1/mTORC1 signalling pathway." (PMID 33773591, 2021). "Some target genes were likely involved in acne development, including AR, IGF1/IGF1R, mTOR, GATA6, Wnt, IL6, FOXO1, PIK3, MYC." (PMID 40625748, 2025). "In nutrient-sensing acne, IGF-1 promotes the nuclear export of forkhead box O1 (FoxO1) by phosphorylating PI3K and Akt, leading to sebum overproduction and altered lipid profile." (PMID 39349732, 2024). "IGF-1 is a key player in acne pathogenesis, and the IGF-1-induced PI3K/Akt/FoxO1/mTOR C1 pathway is considered to be the most important pathway leading to acne pathogenesis." (PMID 38585341, 2024). "IGF-1 signaling, critical in acne development, regulates the PI3K/Akt cascade and FoxO1 activity, impacting lipogenesis and androgen receptor (AR) transactivation and influencing lipid synthesis and sebaceous secretion." (PMID 38791344, 2024). "A dietary change as a low glycemic regimen also booted the nuclear concentration of the factor forkhead box O1 (FOXO1), normalizing the transcription of acne-related genes." (PMID 36678524, 2022). "Many transcription factors such as FoxO1, 1,25-dihydroxyvitamin D and calcium are connected with sebum production, while hyperandrogenemia, hyperinsulinemia, and high levels of insulin growth factor-1 (IGF-1) play a role in acne development." (PMID 40806666, 2025). "A randomized controlled study showed that supplementation with the probiotic Lactobacillus can decrease the gene expression of insulin-like growth factor 1 (IGF1) by 32% and increase the gene expression of forkhead box protein O1 (FOXO1) by 65%, improving the appearance of adult acne." (PMID 37894244, 2023).
acne (continued). "The PI3K/Akt/FoxO1/mTORC1 axis of the Mammalian Target of Rapamycin (mTOR) C1 pathway, induced by IGF-1, is known to be an essential signaling pathway for the pathogenesis of acne." (PMID 35966699, 2022). "Furthermore, mTOR, FoxO1, and serum IGF-1 along with a high-glycemic-load diet may be involved in the development of acne." (PMID 35163615, 2022).
diabetic cardiomyopathy (34 papers, 2014 to 2026). Diabetic cardiomyopathy is a disorder of the heart muscle in people with diabetes. "Increased Foxo1 transcriptional activity has been linked to cardiac dysfunction and diabetic cardiomyopathy." (PMID 39026321, 2024). "FoxO1 is implicated in the pathogenesis of diabetic cardiomyopathy, and has a role in the regulation of dysfunctionalities in cardiac glucose and fatty acid metabolism." (PMID 35069436, 2021). "FOXO1 has also been associated with diabetic cardiomyopathy." (PMID 36407428, 2022). "To characterize the mechanism through which chemotherapeutic drugs down-regulate KLF5 expression in BLBC, we searched the literature and found that FOXO1 induces KLF5 transcription and causes oxidative stress in diabetic cardiomyopathy." (PMID 37588224, 2024). "The top-cited paper is “Metabolic Stress-induced Activation of FoxO1 Triggers Diabetic Cardiomyopathy in Mice” (LCS: 54), published in the Journal of Clinical Investigation (IF: 19.386 according to 2021 JCRTM)." (PMID 36337893, 2022). "This study was aimed to clarify the effects of Ang IV and its downstream mediator forkhead box protein O1 (FoxO1) on diabetic cardiomyopathy." (PMID 34522203, 2021). "QKI-5 can suppress the expression of FoxO1 by reducing FoxO1 mRNA stability in cardiomyocytes, thus acting as a protector against diabetic cardiomyopathy." (PMID 34222237, 2021). "Second, AS1842856, a specific FoxO1 inhibitor, had a similar therapeutic effect on diabetic cardiomyopathy." (PMID 34522203, 2021). "Our previous study suggests that Foxo1 plays an important role in promoting diabetic cardiomyopathy and controlling β‐MHC expression in the development of cardiac dysfunction." (PMID 33547878, 2021). "Cardiac-specific knock-down of FoxO1 prevented the development of diabetic cardiomyopathy, making a strong case for a detrimental role of cardiac FoxO1 during diabetic cardiomyopathy." (PMID 31921839, 2019). "A previous study reported that sustained activation of Foxo1 or Foxo3 leads to diminished insulin responsiveness and impaired glucose metabolism in cardiac myocytes, and Foxo1 activation triggers diabetic cardiomyopathy through downregulation of Irs1 in mice." (PMID 28887535, 2017). "Resveratrol improves cardiac dysfunction and remodelling and attenuates cardiomyocyte apoptosis and oxidative stress injury in diabetic mice, associated with the regulation of autophagic flux through SIRT1/FOXO1/Rab7 axis, which suggests a therapeutic strategy for diabetic cardiomyopathy." (PMID 24889822, 2014). "Therefore, it is hypothesized that FoxO1, as an important mediator of diabetic cardiomyopathy, may become an attractive therapeutic strategy." (PMID 41522193, 2026). "Therefore, it is speculated that FoxO1 is involved in glycophagy as an important mediator in diabetic cardiomyopathy, and it may become an attractive therapeutic strategy." (PMID 41522193, 2026). "In addition, FOXO1 promoted KLF5 transcription in diabetic cardiomyopathy." (PMID 37588224, 2024). "For example, inhibition of the transcription factor forkhead box O1 prevents transcription of Pdk4, which encodes for PDHK4, thereby increasing myocardial glucose oxidation and alleviating the diastolic dysfunction associated with experimental diabetic cardiomyopathy in mice." (PMID 36211560, 2022). "Thus, Ang IV and FoxO1 provide a promising therapeutic target for diabetic cardiomyopathy." (PMID 34522203, 2021). "Thus, inhibition of FoxO1 may provide an alternative approach to the treatment of diabetic cardiomyopathy." (PMID 34522203, 2021). "Administration of resveratrol exerts cardioprotective effects by activating the SIRT1/forkhead box O1 (FOXO1)/Rab7 axis, promoting autophagic flux, alleviating oxidative stress-induced damage, and improving cardiac function in diabetic cardiomyopathy models." (PMID 40734976, 2025).